PIM1 (Pim-1 proto-oncogene, serine/threonine kinase)
Diseases named in the same sentence as PIM1 in open-access papers (continued):
Sharing a sentence is not in itself a finding about the gene and the disease.
tumor (continued). "Here, the authors have found PIM1 overexpression decreases sensitivity to ALK inhibitors in NB and combined ALK and PIM1 inhibition enhances anti-tumour efficacy in vitro and in PDX models." (PMID 31780656, 2019). "This study aims to decipher the prognostic and mechanistic role of PIM1 in progression of SACC cells and tumor tissues." (PMID 29467592, 2018). "These analyses showed a clear list of genes associated to antigen presentation that significantly correlated with PIM1 and PIM2 expression in all tumor types." (PMID 28938604, 2017). "Our data demonstrate that T3 induces miR-214-3p expression and suppresses cell proliferation through PIM-1, thus contributing to the inhibition of HCC tumor formation." (PMID 29093516, 2017). "On Western blot analysis with the tumor lysates from subcutaneous inoculation in mice (SMMC-7721), there was a down-regulation of p-AKT (Ser473) and PKM2 expression in the PIM1 knockdown clone compared with NTC." (PMID 25834102, 2015). "Silencing of PIM1 inhibited HCC proliferation and invasion in vitro and tumor growth and metastasis in vivo." (PMID 25834102, 2015). "The synergistic effect of c-myc and pim1 in tumor development was also shown in methyl methanesulfonate (MMS)-treated AKR mice, where MMS accelerated tumor development." (PMID 24860787, 2014). "Pim-1 plays a significant role on MET expression, the receptor for hepatocyte growth factor (HGF) involved in signaling normal and tumor cell migration and invasion." (PMID 25491234, 2014). "Comparison of gene expression in Set 1 with the Sanger COSMIC dataset identified five down-regulated genes that have previously been confirmed to result in neoplasia; these included CEBPA, ERBB2, EXT1, PIM1, and SDHD." (PMID 25023465, 2014). "Previous studies have demonstrated that αvβ3 regulates the expression of Pim-1 and VEGF, and mediates tumor angiogenesis through the PI3/AKT signaling pathways." (PMID 23119061, 2012). "Multiple lines of transcriptomic evidence in tumor-educated THP1 cells point to STAT3 pathway activation, including upregulation of canonical STAT3 targets (SOCS3, CISH, BCL3, JUNB, PIM1) and increased expression of STAT3-activating ligands (IL6, IL11, LIF, OSM) in response to TNBC contact." (PMID 41514627, 2025). "This drug exerts good efficacy in tumor suppression and osteoclast genesis based on its excellent inhibition of Pim‐1/Pim‐2, and it was a safe and reliable drug, as no significant toxic side effects were found in bone marrow and liver." (PMID 41323479, 2025). "For example, the PIM1/2/3 kinase inhibitor SGI-1776 demonstrated some ability to delay tumor progression without inducing regressions." (PMID 39510293, 2024). "In addition, NOP14 induced expression of transcription factor E2F4 independent of miR17-5p/P130 signaling, which simultaneously activated a set of targeted genes, such as CCNE1, PIM1, AKT1 etc., to promote tumor proliferation." (PMID 37506248, 2023). "Conversely, transient over-expression of PIM1 triggered further increases in tumor mass in two independent PC3 LKB1KO clone xenografts but not in WT samples." (PMID 34193159, 2021). "In PC3 cells, the resulting oncogenic insult could be either suppressed by knocking out all three PIM kinase members or exacerbated by upregulating PIM1 expression, highlighting the integral role of PIM kinases in supporting tumor growth in this setting." (PMID 34193159, 2021). "Additionally, we found that while elevated levels of PIM1 contribute resistance to ADT, the combination of a pan‐PIM‐i and H19 KD can reduce the tumor‐forming capacity of highly aggressive NEPC." (PMID 32146726, 2020). "M1 macrophage-related genes include IL-6, IL-8, CD80, PIM1, RTP4, and SLC11A1, and studies have shown that after metformin treatment, the expression of M1-related factors in tumor cells can be enhanced or weakened, thus affecting the prognosis of the tumor." (PMID 33193731, 2020).
tumor (continued). "While CAPZA1, CAPZA2 and CAPZB, but not CAPZA3 levels correlated well with PIM1 levels in all tumor tissues, similar correlations were also observed for PIM2 and PIM3 in the samples with high Gleason scores." (PMID 32771000, 2020). "The expression of PIM1 was not correlated with conventional clinicopathological parameters such as age, tumour subtype, histological grade, clinical stage or Ki67 expression." (PMID 32307917, 2020). "Moreover, in tumor nodes, knockdown of HOMA11-AS markedly increased the expression of miR-214-3p and reduced the expression of PIM1." (PMID 31275988, 2019). "Overexpression of PIM1 correlates with overexpression of STAT3 in ATLL patient samples, and treatment of ATLL cell lines with a Pim1 inhibitor, AZD1208, led to decreased proliferation, while treatment of ATLL mice with AZD1208 led to decreased tumor formation." (PMID 31684088, 2019). "In this connection, PIM1, as a quick responder to tumor hypoxia, may be capable of facilitating HCC cells to adapt to the harsh survival environment and promote tumor growth and progression." (PMID 25834102, 2015). "Furthermore, PIM1 reprogramed HCC metabolism and facilitated tumor cell glycolysis, which in turn sustained tumor growth and enhanced tumor invasion." (PMID 25834102, 2015). "Overexpression of PIM-1 leads to tumor formation in mice, while complete PIM-1 knockout has no observable phenotype." (PMID 25040935, 2014). "By crossing heterozygous animals of both genotypes, it was observed that Eμ-c-myc;Eμ-pim1 mice expressing high levels of c-myc were not viable, whereas Eμ-c-myc;Eμ-pim1 mice expressing low levels of c-myc were viable and showed a low tumor incidence." (PMID 24860787, 2014). "However, knockout of PIM1 was sufficient to significantly reduce tumor cell protrusive activity and invasion regardless of oxygen tension, suggesting that basal levels of PIM1 are important for proper cell migration." (PMID 37042842, 2023). "PIM1 might act upstream of cluster 27, which in turn is upregulated in EGFR WT tumor samples." (PMID 35360705, 2022). "Furthermore, Pim-1 knockdown couldsuppress HCC proliferation and invasion in vitro and tumor growthand metastasis in vivo." (PMID 31359998, 2019). "Tumours adapt to chronic hypoxia inducing changes in gene expression through the activation of pro-survival and metastatic genes such as nuclear factor kappa beta (NF-κB), Hypoxia-inducible factor-1-alpha (HIF-1-α), PIM-1 oncogene (PIM-1) and endothelin-1 (EDN 1)." (PMID 30595759, 2018). "PIM1 expression has been reported to be modulated at transcriptional level through activation of JAK/STAT pathway in physiological conditions, however, its differential expression in tumor vs. normal cells might be induced through deregulation of microRNAs." (PMID 28947967, 2017). "While Pim1 is a weak oncogene with little or no role in tumor initiation, it may play a role in tumor progression." (PMID 23565217, 2013). "In addition, tumour tissue from patient #3 displayed higher PIM1 and ERG levels than the corresponding autologous non-malignant prostate." (PMID 22140532, 2011). "Therefore, inhibition of either STAT3/STAT5 signaling or PIM1/FATP2 expression in tumor-bearing mice in vitro could significantly attenuate MDSC-mediated immunosuppressive effects on tumors, thereby improving the anti-tumor response of CD8+ T-cells." (PMID 39227970, 2024). "However, a role for PIM1 in tumor cell invasion and metastasis has not been described." (PMID 37042842, 2023). "Though Pim-1 expression is not required for BCR/ABL-mediated transformation, it does benefit tumor cell survival." (PMID 36694243, 2023). "Silencing of PIM1 suppressed HCC cell invasion in vitro as compared to non-target control, and decreased HCC cell proliferation in vitro and tumor growth and metastatic potential in vivo." (PMID 25834102, 2015).
tumor (continued). "Quantitative Real-Time PCR analysis of an ERG-positive tumour and the corresponding non-tumoral adjacent tissue validated the connection between ERG and PIM1 at the transcriptional level." (PMID 22140532, 2011). "Not being a HIF target, PIM1 enhances AKT-mediated glycolysis by activating the phosphorylation of AKT and hence its downstream targets to produce energy and maintain HCC growth and progression in the hypoxic tumor microenvironment." (PMID 25834102, 2015).
infection (18 papers, 2010 to 2026). The state of being infected such as from the introduction of a foreign agent such as serum, vaccine, antigenic substance or organism. "Indeed, we observed rapid TgIST-dependent depletion of PIM1 upon infection with Tg, further precipitating the loss of GBP1 phosphorylation and interaction with 14-3-3σ." (PMID 37797010, 2023). "Collectively, the results suggest that AZD1208 treatment following ME49 infection correlates with increased apoptotic markers in murine spleen tissue, implying that PIM1 facilitates ME49 replication by suppressing apoptosis in vivo." (PMID 41557744, 2026). "Restricted to an acute-infection model, this study elucidates the role of the host protein PIM1, a serine/threonine protein kinase, in facilitating T. gondii proliferation and its potential as a therapeutic target." (PMID 41557744, 2026). "Subsequently, we preliminarily explored the mechanism by which PIM1 inhibits apoptosis within cells following ME49 infection." (PMID 41557744, 2026). "To gain a better understanding of the effect of Pim1 on myoblast behaviors, we established Pim1 low-expression and over-expression C2C12 myoblast cell lines by Lv-shPim1 or Lv-Pim1 infection." (PMID 31601787, 2019). "As expected, infection with Lv-shPim1 efficiently downregulated, while infection with Lv-Pim1 upregulated Pim1 protein level in C2C12 myoblasts." (PMID 31601787, 2019). "In our study, Tyrosine kinase 2 (TYK2, one of the JAKs) and its negative regulators SOCS1, SOCS3 as well as anti-apoptosis genes BCL-XL and PIM1 were differentially regulated by IRF7 during the H6N2 infection." (PMID 30356848, 2018). "As a result, infection of shPIM-1 lentivirus resulted in a remarkable reduction in PIM-1 protein expression, which in turn significantly reduced PASMCs proliferation both with and without PDGFBB treatment." (PMID 27448984, 2016). "Our results from the primary infection studies suggested a major contributory role of EBNA3C in inducing Pim-1 expression." (PMID 25121590, 2014). "The Eμ-pim1 mouse model has been broadly used to study oncogenic cooperation by infection with M-MuLV and by crosses with other transgenic models; this model has also been extensively used for carcinogen testing." (PMID 24860787, 2014). "Similar results were obtained following infection of BJ fibroblast with PIM-1-expressing retrovirus." (PMID 25040935, 2014). "PIM kinases (PIM1, PIM2, PIM3) are serine/threonine kinases implicated in infection and reactivation of various viruses, but their roles in HIV-1 gene expression and particle production remain unclear." (PMID 41754420, 2026). "Knockdown of Snhg15 during VEEV TC-83 infection resulted in the suppression of ten genes including Irf1, Junb, Atf3, Relb, Pim1, Hbegf, Ccl5, Ankrd33b, and H2-K2, all of which were also increased during TC-83 infection when the expression of Snhg15 increased in primary mouse astrocytes." (PMID 40463150, 2025). "Interestingly, infection with ΔEBNA3C BAC-GFP-EBV resulted in low Pim-1 expression at 2 days post-infection and returned to the levels seen for infected cells at 0 day post-infection." (PMID 25121590, 2014). "The mRNA and protein levels of Pim-1 were detected after 0, 2, 4, 7 days of infection." (PMID 25121590, 2014). "Interestingly, infection with the ΔEBNA3C BAC-GFP-EBV showed a much lower Pim-1 expression at 2 days post-infection." (PMID 25121590, 2014). "Pim-1 was substantially induced in neointimal VSMC of balloon injured rat carotid arteries, and in vivo infection with a dominant-negative Pim-1-expressing adenovirus (Ad-DN-Pim-1) markedly suppressed neointima formation and cell cycle progression in the balloon injured arteries." (PMID 20182627, 2010). "Through mitochondrial isolation, we found that upon infection, the suppression of PIM1 led to a reduction of cytochrome c within the mitochondria and an increase of cytochrome c released into the cytoplasm, suggesting that it may inhibit apoptosis through the mitochondrial pathway." (PMID 41557744, 2026).
infection (continued). "Infection with STAT3-shRNA reduced the mRNA levels of ROR1 and the Stat3-regulated genes STAT3, Bcl2, Bcl-XL, Cyclin D1, c-Myc, WAF1/p21, and Pim1." (PMID 20686606, 2010). "When A549 cells infected with ZIKV at an MOI of 0.1 were treated with the PIM1 inhibitor SGI-1776, both the intracellular envelope protein level and the RNA level of ZIKV were markedly suppressed by SGI-1776 in a dose-dependent manner at 48 h post-infection." (PMID 39679197, 2024). "Supporting this finding, we did not observe degradation of PIM1 or dephosphorylation of GBP1 upon STm-infection." (PMID 37797010, 2023). "Treatment with 2-pyridone PIM1 inhibitor was able to significantly downregulate Notch1, Notch2, CTNNB1, and CDC42 in SARS-CoV-2-infected cells at 24 h post-infection (p-value < 0.001)." (PMID 37211584, 2023).
hematologic malignancies (14 papers, 2009 to 2025). "PiM1 alleles and PiM1 homozygotes are both associated with hematological malignancies, although this is considered a functionally normal AAT variant." (PMID 21637443, 2009). "Since enhanced levels of Pim-1 is linked to different hematological or non-hematological malignancies, it reveals the intricate mechanisms that are linked to ubiquitin-proteasome-mediated degradation of Pim-1 and is important for designing therapeutic interventions." (PMID 25121590, 2014). "To conclude, the higher frequency of PiM1 homozygotes and PiM1 allele in patients with hematological malignancies could be a consequence of a so far unknown association between the main serine protease inhibitor and hematological malignancies." (PMID 21637443, 2009). "PIM1, a serine/threonine kinase, is known to be overexpressed predominantly in hematologic malignancies and is a downstream target of HOXA9, especially in AML with FLT3-ITD mutations." (PMID 40746924, 2025). "The family of pim kinases comprises three isozymes: pim‐1, pim‐2, and pim‐3, all of which are reported to be overexpressed in several hematologic malignancies." (PMID 37162273, 2023). "It has universally acknowledged the critical role of PIM1 in the occurrence and development of hematological malignancies and identified as the target of abnormal somatic hypermutation in DLBCL." (PMID 35937947, 2022). "Proviral integration site for Moloney murine leukemia virus 1 (Pim-1) is a serine/threonine kinase first reported in hematological malignancies." (PMID 29179437, 2017). "Contrasting with PIM1 and PIM2, PIM3 is ubiquitously and uniformly expressed across hematologic malignancies, and is also more highly expressed in solid tumors (eg, pancreatic, gastric, and colon cancers)." (PMID 29927999, 2018).
adenocarcinoma (5 papers, 2013 to 2023). A common cancer characterized by the presence of malignant glandular cells. "A publicly available Kaplan–Meier analysis of fourteen transcriptomic databases including TCGA indicates a significant association between PIM1 mRNA levels in lung squamous/adenocarcinoma patients and reduced progression free survival (n = 982 HR = 1.28, p = 0.011)." (PMID 33946744, 2021).
hematological cancer (5 papers, 2012 to 2022). "Although investigations into the regulation of Pim-1 expression have largely focused on leukocyte models, recent findings that Pim-1 is overexpressed in some non-hematopoietic cancers (above) suggest that mechanisms limiting its induction may be relevant to many different cell types." (PMID 22413002, 2012).
prostate (4 papers, 2010 to 2019). "Of particular relevance for T. vaginalis infection, we have demonstrated that T. vaginalis contact leads to increased PIM1 expression in PECs, providing a possible molecular mechanism by which T. vaginalis contributes to prostate carcinogenesis." (PMID 22912571, 2012). "We show here that tERG expression induces PIM1 in the non-malignant prostate cell line RWPE-1, strengthening the relation between tERG and PIM1 up-regulation in the initial stages of prostate carcinogenesis." (PMID 22140532, 2011). "Our results suggest an in vivo role of Pim1 in promoting prostate tumorigenesis although it displayed distinct oncogenic activities depending on the disease stage of the cell line." (PMID 20515470, 2010). "Our results suggest three intracellular protein targets CDK6, PIM1 and MAPK/p38 that have been reported to play an important role in colorectal carcinogenesis." (PMID 30655588, 2019).
immune disease (2 papers, 2018 to 2021). "Our results showed a panel of three downregulated miRNAs (hsa-miR-4516, hsa-miR-494-3p and hsa-miR-542-3p) involved in the regulation of genes associated with viral latency (SUPT16H, TFPI), HIV reactivation (PIM1) and persistent metabolic and immune disorders (ZADH2, CCL16)." (PMID 34829855, 2021).
myopathy (1 paper, 2019). A disease of the muscle in which the muscle fibers do not function properly. "H&E staining also showed that Pim1−/− mice has no severe myopathy characterized by central nucleated myofibers from birth to 12-week old." (PMID 31601787, 2019).
PIM1 also shares sentences with these, for which no sentence is quoted: multiple myeloma (5 papers); abdominal aortic aneurysm (2); Alzheimer disease (2); celiac disease (2); mesothelioma (2); non-Hodgkin lymphoma (2); salivary gland adenoid cystic carcinoma (2); acute kidney injury (1); adult T-cell leukemia (1); airway hyperresponsiveness (1); Airway obstruction (1); anemia (1); Anxiety (1); bladder tumors (1); brain cancer (1); breast adenocarcinoma (1); carcinoid tumour (1); carcinoma of the tongue (1); cervical adenocarcinoma (1); cervical cancer (1); chronic kidney disease (1); chronic pancreatitis (1); coronary atherosclerosis (1); cutaneous T cell lymphoma (1); depression (1); diabetic retinopathy (1); endometrial tumors (1); ependymoma (1); erythroblastic leukemia (1); esophageal cancer (1).
A further 31 diseases each share a sentence with PIM1 in 1 paper.